IL10 (interleukin 10)
Diseases named in the same sentence as IL10 in open-access papers (continued):
Sharing a sentence is not in itself a finding about the gene and the disease.
hepatocellular carcinoma (continued). "The finding stays in agreement with the data on the enhancement of the hsp90 gene expression by IL-10 in a human hepatoma HepG2 cell line and peripheral blood mononuclear cells." (PMID 16246258, 2005). "Indeed, the IL-4, IL-6, and IL-10 levels were found to be higher in patients with ascites and hepatocellular carcinoma (HCC) than patients with cirrhosis alone." (PMID 40149656, 2025). "Similarly, in hepatocellular carcinoma, B cell activation by dendritic cells via IL-10 aids in the tumor’s evasion of immune surveillance." (PMID 39519376, 2024). "Overall, IL-10 (-1082 A/G) showed a tendency toward significant relationship with hepatocellular carcinoma under heterozygous model (OR: 0.82, 95%CI:0.67-1.0, I2 = 49%, fixed effect model, 9 studies), however other four genetic models did not (All p values > 0.05)." (PMID 37684564, 2023). "The findings suggested that IL-10 -1082 A/G and − 819 T/C have some roles in associated risk of hepatocellular carcinoma in the non-Asians group." (PMID 37684564, 2023). "On the other hand, the decrease in serum IL-10 suggested that WCP against hepatocellular carcinoma might occur through an IL-10-regulated signaling pathway, so we examined its downstream STAT3 and p-STAT3 proteins." (PMID 37110586, 2023). "IL-10 (-819 T/C) was significantly associated with hepatocellular carcinoma risk only among non-Asians under the dominant (OR: 1.47, 95% CI: 1.02–2.13, 8 studies), recessive (OR: 1.99, 95% CI: 1.03–3.86, and homozygous models (OR: 2.18, 95% CI: 1.13–4.23)." (PMID 37684564, 2023). "There are published meta-analyses that assessed IL-10 on hepatocellular carcinoma." (PMID 37684564, 2023). "Furthermore, the Tnf gene can induce multiple mechanisms to initiate hepatocyte apoptosis, leading to subsequent liver injury, and Ereg and IL10 are up-regulated in acute liver injury and hepatocellular carcinoma, respectively." (PMID 36389730, 2022). "In the serum of patients with hepatocellular carcinoma and supernatants of peripheral monocytes cocultured with Huh7 cells, the levels of cytokines (IL-4, IL-6, and IL-10) could be upregulated, while the level of IFN-γ could be downregulated." (PMID 33435880, 2021). "Our results showed that the production of IL-4, IL-6, and IL-10 in H22 hepatoma bearing mice treated with DCs stimulated by ESPs was significantly reduced, while the expression of IFN-γ was markedly increased, which was the opposite to the cytokine expression in the ESP group." (PMID 32692308, 2020). "In addition, the correlation between TGF-β and Tregs was also confirmed in hepatic carcinoma patients and the expression of both TGF-β and IL-10 was shown to be associated with hepatic carcinoma progression, as well as PDAC." (PMID 30359281, 2018). "Current evidences show that B cells expressing IL-10 could suppress the activities of cytotoxic CD4+ T cells in hepatocellular carcinoma, leading to the poor prognosis." (PMID 28234961, 2017). "Thus, IκBα-mediated early activation of monocytes in hepatoma environments is vital for semimature DC-elicited B-cell activation and IL-10 production." (PMID 27853178, 2016). "To determine whether IL-19 promotes the expression of TNF-α and IL-10, we analyzed the effect of IL-19 on the HepG2 human hepatoma cell line." (PMID 23468852, 2013). "In melanoma and hepatocellular carcinoma (HCC), miR-98 suppresses IL-6 and IL-10 expression, respectively, influencing tumor cell migration and invasion, thereby impacting patient survival." (PMID 39731171, 2024). "On stratification, IL-10 (-1082 A/G) was significantly associated with hepatocellular carcinoma risk in the non-Asian population under dominant (OR: 0.62, 95% CI: 0.45–0.86, 4 studies), heterozygous (OR: 0.60, 95% CI: 0.43–0.85) and allelic models (OR: 0.79, 95% CI: 0.64–0.99)." (PMID 37684564, 2023).
hepatocellular carcinoma (continued). "Based on limited data presented in this review, we still do not know whether IL10 gene polymorphisms (-1082 A/G and − 819 T/C) increases or reduces the risk of hepatocellular carcinoma." (PMID 37684564, 2023). "Therefore, given these data and previous investigators reported observations that IL-10 could directly affect cholesterol synthesis biology in human hepatocellular carcinoma cells in vitro, we investigated PEG-rMuIL-10’s effect on liver biology." (PMID 27299860, 2016). "Interleukin-10 (IL-10) and interleukin-6 (IL-6) have been reported to be related to hepatocellular carcinoma (HCC) prognosis." (PMID 27335826, 2013). "This study highlights the critical role of IL-6, IL-10, and liver function markers (AST and ALT) in the progression and prognosis of hepatocellular carcinoma (HCC)." (PMID 41379186, 2025). "The other study demonstrates that HILPDA upregulate IL-10 to activate the STAT3 signaling pathway in NK cells, which promotes hepatocellular carcinoma immune evasion and progression." (PMID 40861438, 2025). "Other experiment has shown that IgA+ plasma cells that highly express PD-L1 and IL-10 accumulate in people and mice with nonalcoholic steatohepatitis, directly inhibiting CTL activation and finally promoting hepatocellular carcinoma." (PMID 36601120, 2022). "Considering HBV progression, the levels of IL-1β, IL-17, IL-10, IP-10, MCP-1, and MIP-1β were all markedly decreased in the hepatoma group compared to that in the CHB group." (PMID 35785033, 2022). "Human hepatoma cells and primary murine hepatocytes were treated with TNF-α/LPS/IL-6/IL-10 and USP18, phosphorylated (p)-STAT1 and myxovirus (influenza virus) resistance 1 (Mx1) expression was determined." (PMID 27009955, 2016). "C3 secretion induced by Piwi Like RNA-Mediated Gene Silencing 1 protein (PIWIL1) in human hepatocellular carcinoma (HCC) cells leads to the activation of p38 and MAPK signalling in MDSCs, which, in turn, triggers the expression of immunosuppressive cytokine IL-10 in these cells." (PMID 35860237, 2022). "Meanwhile, it increased NK cells’ cytotoxicity in spleen, down-regulated the amount of CD4+CD25+Foxp3+ Treg cells and Th17 cells in tumor tissue, and decreased IL-10, TGF-β, and IL-17A levels (P < 0.01) whereas increased IL-2 and IFN-γ levels (P < 0.01) in the serum of hepatoma H22-bearing mice." (PMID 28086772, 2017). "Conversely, it was found that upon inhibition of mTOR in macrophages in hepatocellular carcinoma (HCC), STAT3 decreased the secretion of both IL-10 and IL-12 and inhibited angiogenesis in vivo." (PMID 39003350, 2024). "IL-10, transforming growth factor beta (TGF-β), and Wnt ligands from hepatocellular carcinoma (HCC) cells upregulate Wnt2b expression and promote M2 polarization in TAMs by activating the Wnt2b/β-catenin/c-Myc signaling axis and glycolysis." (PMID 39430253, 2024). "This contest allowed us to hypothesize that ANXA1 could affect the macrophages by activating its receptor FPR, as described in the hepatocellular carcinoma where this protein is able to enhance the differentiation into M2 macrophages via FPR2 and supports their expression of IL-10." (PMID 34681678, 2021). "For instance, DCs pulsed with hepatocellular carcinoma cell (HCC)-derived exosomes led to an increase in IFNγ levels and CD8+ T cells, and in the reduction of IL10 and TGF-β levels in HCC-bearing mice." (PMID 29515996, 2018). "In a hepatocellular carcinoma (HCC) mouse model, treatment with DCsEVs derived from alpha-fetoprotein (AFP)-expressing DCs elevated the numbers of INF-γ-expressing CD8 + T cells and decreased the secretion of IL-10 and TGF-β." (PMID 36167539, 2022). "In addition, in this study, WCP was discovered to inhibit hepatocellular carcinoma, possibly by promoting apoptosis through the promotion of Cyto-c/Caspase8/3 and inhibition of IL-10/STAT3/Bcl2 signaling pathways, which will advance our understanding of WCP as a potential therapeutic option for HCC." (PMID 37110586, 2023).
hepatocellular carcinoma (continued). "Interleukin-10 (IL-10), an anti-inflammatorycytokine, plays an important role in modulating the human immune system, and ithas been used to evaluate the long-term outcomes of solid tumors and non-solidtumors, such as hepatocellular carcinoma (HCC), and non-Hodgkin’s lymphoma." (PMID 40026520, 2025).
Granuloma (98 papers, 2006 to 2026). A compact, organized collection of mature mononuclear phagocytes, which may be but is not necessarily accompanied by accessory features such as necrosis. "Increased levels of IL-4 and IL-10 can affect Mtb-induced granuloma and are linked to an increased bacterial burden, and more severe TB and LTBI recurrence." (PMID 39514524, 2024). "Considering the effects observed in IL-10/IL-12-deficient mice, the improvement of fibrotic granulomas seemed to be dependent on the fine-tuning of Il4, Il10, and Il12." (PMID 39404406, 2024). "In granuloma formation, IL-10 acts as a negative regulator of the immune response and high levels of IL-10 are strongly associated with a disorganization of granuloma structure." (PMID 31475008, 2019). "Our prior data suggested that the combination of T cells expressing IL-10 and T cells expressing a pro-inflammatory cytokine in granulomas was associated with the sterilization of Mtb granulomas." (PMID 30312351, 2018). "We previously published that IL-10+ T cells in conjunction with T cells producing a proinflammatory cytokine (i.e. IL-17) in individual granulomas was associated with lower bacterial burdens, including sterility." (PMID 30312351, 2018). "In cynomolgus macaques, we show that even when granulomas are established, some LNs are able to clear Mtb and these LNs are associated with higher CD11b+ cells producing IL-10." (PMID 30383808, 2018). "Granulomas from high-risk animals had higher frequencies of IL-17, IL-10 or IL-2 producing CD3+ T cells as compared to granulomas from low risk animals." (PMID 27379816, 2016). "Infection with B. abortus resulted in the formation of liver granulomas and necrotic lesions in both IL-10 KO and wild-type mice which was associated with a decrease in volumetric proportion of the parenchyma." (PMID 24069337, 2013). "Although the mechanism of IL-10 in sarcoidosis is unclear, it is thought to be associated with granuloma resolution." (PMID 22393278, 2012). "IL-10 has been found to be associated with susceptibility to chlamydial infection and typical pathological changes caused by the infection such as granuloma formation and fibrosis." (PMID 19397832, 2009). "In case of chlamydial infection IL-10 has been reported to be associated with typical pathological changes like fibrosis and granuloma formation." (PMID 18828896, 2008). "More studies should be conducted to investigate whether the observed increases in cytokines IFN-γ, TNF-α, IL-2, and decrease in IL-10 found in granuloma supernatants is indeed the cause of the decreased burden of mycobacterial." (PMID 34150674, 2021). "Total IL-10 coverage directly correlated with neutrophil influx within caseous granulomas, with HIV coinfection associated with a small reduction in this correlation (M. tuberculosis–monoinfected persons, R2 = 0.6936, P = .0001; coinfected persons, R2 = 0.3906, P = .0004)." (PMID 27462092, 2016). "This suggests that a blocking of the normal secretion of IL-10, due to inflammation, might be a mechanism related to the risk of granuloma formation in sarcoidosis." (PMID 25180094, 2014). "In the present study, B cells cocultured with Mtb-infected monocytes significantly increased IL-1Ra, IL-18, and IL-10 production, suggesting a possible role of IL-10–producing Bregs in regulating excess inflammation in granulomas." (PMID 41208111, 2025). "Elevated levels of the immunosuppressive cytokine IL-10, frequently observed in granulomas, suppress macrophage activation, dendritic cell function, and T-cell recruitment." (PMID 40004082, 2025). "Five traits: lung granuloma necrosis (“Necr Ratio”), weight loss, MMP8, CXCL1, and IL-10 mapped to Dots8." (PMID 38861581, 2024). "Our present work expanded these findings, identifying several T, NK cell subpopulations, including terminally differentiated and cytotoxic CD8-enriched subpopulations as putative sources of IL10 production in TB granulomas." (PMID 39214090, 2024).
Granuloma (continued). "By day 45 of treatment with PZA or INH, the lung tissue of IL-10 KO mice contained fewer granulomas than water-treated controls, although this difference was not statistically significant." (PMID 37279084, 2023). "From this characterisation it was observed that stage I early granulomas expressed more IL-17A and IL-10 when compared to late-stage granulomas (stage IV)." (PMID 37901102, 2023). "Evaluation of lung tissue supported these findings, with only one mouse having a granuloma in PZA-treated IL-10 KO mice relative to three to four mice with one or more granulomas in INH-treated IL-10 KO or WT PZA-treated mice." (PMID 37279084, 2023). "Lung tissue sections from IL-10 KO mice receiving water had fewer lung granulomas than WT mice at each time point and showed development of mature granulomas characteristic of this mouse strain." (PMID 37279084, 2023). "Studies in both experimentally and naturally infected cattle using ISH and IHC, demonstrated a positive correlation between granuloma stage and IL-10 mRNA expression, with the strongest immunoreactivity for IL-10 protein in stage IV granulomas." (PMID 35056009, 2022). "Large amounts of IL-4 are produced in S. mansoni-infected mice and are proposed to be responsible for granuloma formation, and cytokine IL-10 is fundamental for generating host-protective homeostatic circumstances in schistosomiasis." (PMID 36362992, 2022). "Nevertheless, at the levelof individual granulomas, B cell contributions to bacterial control,production of IL-6 and IL-10, as well as diminishing the frequency of Tcells expressing IL-2, IL-10, or IL-17 have been reported." (PMID 33857251, 2021). "Though no change in outcome was seen, there was a significant increase in IL-2, IL-10 and IL-17 producing T cells within rituximab treated macaques, though IL-6 and IL-10 levels were lower in the granulomas themselves." (PMID 32189035, 2020). "Patients with a fungal infection and sarcoidosis have low levels of IL-10 within the serum resulting from granuloma formation which blocks IL-10 secretion." (PMID 32801570, 2020). "After 15 days of infection, the IL-12 and IFN-γ levels tended to be higher, and IL-10 lower when Mtb infected granulomas derived from PBMCs obtained from healthy subjects were treated with MFS compared to the sham-treated infected-control." (PMID 30823377, 2019). "IL-10 levels tended to be lower when Mtb infected granulomas from healthy subjects were treated with MFS compared to the sham-treated infected-control after 15 days." (PMID 30823377, 2019). "As IL-17 and IL-10 expression and secretion were strongly increased in Mtb-induced granuloma upon etanercept, we wondered if it was also modulated in cell-cell fusion assay." (PMID 31475008, 2019). "Type-2 cytokines, such as IL-5, IL-4, and IL-13, are responsible for the recruitment and activation of immune cells involved in granuloma formation, whereas IL-10 has been related to the granuloma modulation." (PMID 31886307, 2019). "The absence of these cytokines, or the inability to signal via the IL-4Rα in BALB/c mice, results in a reduced IFN-γ response, severely limited granuloma development, enhanced IL-10 production and disease exacerbation." (PMID 31475014, 2019). "The increased levels of Foxp3 and Il10 mRNA found in the encapsulated granuloma center support a local suppression of pulmonary inflammatory cells." (PMID 31015452, 2019). "The IL-10+ T cell responses in reinfection granulomas were similar to those in the primary (library A) infection granulomas in the same macaques." (PMID 30312351, 2018). "INH+NAC treatment of granulomas from subjects with T2DM also resulted in a significant increase in the production of IL-10." (PMID 30258443, 2018). "We interpret this to mean that either an immune balance of pro- and anti-inflammatory cytokines is a robust pathway to sterilization in granulomas, or that the IL-10 signal is a sign of granuloma healing once bacteria have been killed." (PMID 30312351, 2018).